INS (insulin)
Diseases named in the same sentence as INS in open-access papers (continued):
Sharing a sentence is not in itself a finding about the gene and the disease.
diabetes (continued). "However it is possible that in some of our transgenic mice, enough (pro)insulin was produced to prevent diabetes." (PMID 15679918, 2004). "Meanwhile, CHIR99021 potentiates insulin activation of glucose transport and utilisation in vitro and in vivo, and related compounds reduce muscle insulin resistance in animal models of diabetes." (PMID 15350195, 2004). "Diabetes results in higher circulating insulin and glucose levels and perhaps higher free insulin-like growth factor I, which may be growth enhancing and therefore increase prostate cancer risk." (PMID 15150583, 2004). "Furthermore the expression of (pro)insulin in hepatocytes is insufficient to prevent development of diabetes in NOD mice." (PMID 15679918, 2004). "There was a disparity by diabetes status, such that the association between +1127 INS-PstI and prostate cancer was apparent among subjects without diabetes (OR=2.18) but not among those with diabetes (OR=1.13)." (PMID 12610512, 2003). "Previous studies reported that there were associated with insulin and hepatic insulin resistance even in the absence of diabetes in subjects with steatohepatitis, fatty liver, and NASH." (PMID 12587609, 2003). "The association between prostate cancer and the +1127 INS-PstI marker could be muddled in the diabetics – a heterogeneous group with diverse aetiology, type, and treatment of diabetes as well as endogenous and exogenous insulin." (PMID 12610512, 2003). "Of paramount interest has been thepotential interaction(s) between leptin and insulin.Insofar as insulin alters leptin secretion/action (orvice versa), dysregulation of this system could contributeto disease states such as diabetes." (PMID 12369715, 2001). "Ketoacidosis typically occurs in patients with type 1 diabetes who completely lack insulin." (PMID 15706798, 1998). "Ketoacidosis is caused by complete or near-complete lack of insulin and by excessive glucagon levels." (PMID 15706798, 1998). "Castrate female rats given weekly applications of DMBA to the genital tract and treated additionally with growth hormone, insulin or alloxan (to induce diabetes) are heavier and have more sarcomatous and epithelial cervico-vaginal neoplasms than intact animals under the same experimental conditions." (PMID 4335634, 1971). "Thyroid nodule (TN) prevalence is rising globally, with particularly high rates among patients with type 2 diabetes mellitus, where insulin resistance and hyperinsulinemia may promote nodule formation via the thyroid-stimulating hormone (TSH)/insulin-like growth factor-1 axis." (PMID 41650047, 2026). "Relevant to the diabetes research field, activation of the alternative pathway of complement leads to C3 cleavage and release of the bioactive peptide C3a, which augments glucose-stimulated insulin secretion from beta-cells via stimulation of the C3a receptor (C3aR)." (PMID 41386533, 2026). "Some research suggests that exposure to insulin autoantibodies (IAA) does not increase diabetes risk in non‐obese diabetic (NOD) mice, while other studies report a higher prevalence of beta cell‐specific autoantibodies in the umbilical cord blood of offspring who later develop T1DM." (PMID 41573056, 2026). "We describe a 38-year-old woman with early-onset insulin-requiring, autoantibody-negative diabetes, progressive visual loss due to optic atrophy, bilateral sensorineural hearing loss, secondary amenorrhea with hyperprolactinemia, and arginine-vasopressin (AVP) deficiency." (PMID 42093864, 2026). "Additionally, γ-terpinene, one of the primary active components in cumin (Cuminum cyminum) essential oil, has therapeutic effects on diabetes, including reducing serum levels of glycated hemoglobin, triglycerides, and cholesterol, while increasing insulin levels." (PMID 41544100, 2026).
diabetes (continued). "According to the Diabetes Control and Complications Trial, patients who were intensively managed were those taking multiple injections of insulin (three or more) per day or using an insulin pump along with monitoring of blood glucose levels four or more times per day." (PMID 41601933, 2026). "Diabetes mellitus (DM) represents one of the most common and fastest-growing metabolic conditions worldwide, with chronic hyperglycemia due to errors in insulin secretion, action, or both." (PMID 41602471, 2026). "Furthermore, early intervention with non‐insulin antihyperglycemic medications for control of new‐onset prediabetes/diabetes may be crucial in preventing the need for insulin prescription and worsening of survival." (PMID 41287203, 2026). "A recent systematic review and meta-analysis confirmed that T1D is associated with increased risk of ED compared with individuals without diabetes (RR = 2.47, 95% CI = 1.84–3.32, p < 0.00001) and reports a prevalence of insulin omission/restriction at 10.3%, predominantly in females." (PMID 41484931, 2026). "Given that insulin modulates FMO3 activity within hepatocytes, circulating TMAO concentrations might reflect underlying hepatic insulin resistance, offering a possible mechanistic link to its reported associations with diabetes and cardiovascular risk." (PMID 41685376, 2026). "Finally, in ketosis-prone diabetes, C-peptide may predict ability to discontinue insulin following diabetic ketoacidosis (DKA)." (PMID 41355468, 2026). "This association may reflect treatment‐specific effects, including the potential mitogenic properties of insulin, but could also reflect the severity of underlying metabolic dysfunction in patients with more advanced or difficult‐to‐control diabetes, which necessitates the use of insulin therapy." (PMID 41287203, 2026). "Thus, dysfunction of RNA-binding proteins may, at least in certain cases, contribute to the impaired insulin production observed in diabetes." (PMID 41786146, 2026). "Indeed, it is known that thanks to KD patients with T2DM can reduce and stabilise glucose levels (fasting, after meals and throughout the day), lower HbA1c and insulin levels, reduce body weight, and reduce (or even wean off) diabetes medication, often achieving full remission." (PMID 41486865, 2026). "Background/Objectives: Periodontitis and diabetes mellitus (DM) are chronic inflammatory conditions that share common biological mechanisms, including systemic inflammation and insulin resistance." (PMID 41975764, 2026). "Although these agents are associated with a lower risk of hypoglycemia compared to other diabetes medications such as sulfonylureas or insulin, hypoglycemia remains a reported side effect—even in clinical trials involving patients with obesity and no underlying diabetes." (PMID 41356535, 2026). "In addition, we showed in clinical research that insulin therapy at an early stage of diabetes increased the possibility of withdrawal of insulin and that results in glucagon test or casual C-peptide index were useful to predict the possibility of withdrawal from insulin." (PMID 41585322, 2026). "Therefore, HUA not only directly affects the blood sugar level, but also may accelerate the occurrence and development of diabetes by interfering with the normal physiological function of insulin." (PMID 40092731, 2025). "However, in studies of type 2 diabetes caused by hepatitis C virus infection, it is shown that KCNQ1OT1 was found to promote the scorch death of β-cells infected by hepatitis C virus through the miR-223-3p/NLRP3 axis, thereby affecting insulin production and accelerating the onset of diabetes and." (PMID 41334450, 2025). "Diabetes mellitus (DM) is a chronic metabolic disorder characterized by persistent hyperglycemia due to impaired insulin secretion, defective insulin action, or both." (PMID 40978922, 2025).
diabetes (continued). "Indeed, improving insulin sensitivity before the onset of type 2 diabetes mellitus may help to prevent or slow down the development and progression of atherosclerosis." (PMID 40573102, 2025). "Furthermore, it shows a clear rela- tionship between the history of diabetes, insulin levels, and HOMA-IR, discovered as the most dominant biomarkers when we applied the Shapley additive explanations (SHAP) method to clarify features’ contribution and importance to the predicted GDM risk." (PMID 40082942, 2025). "In participants with T1D, insulin-stimulated glucose disposal, and blood volume (capillary recruitment) in the forearm microvasculature were both severely impaired and positively associated with each other, independent of HbA1c, BMI, and diabetes duration." (PMID 39998445, 2025). "Although impaired insulin signaling in AD is distinct from that in diabetes mellitus, the peripheral glycolysis‐related alterations identified in our analysis may represent an early warning sign of broader systemic endocrine changes that reflect underlying neuroendocrine disturbances." (PMID 41383880, 2025). "Furthermore, insulin’s role as an anabolic hormone can influence thyroid hormone concentrations; it has been shown to enhance T4 concentration while suppressing T3 concentration, further complicating the hormonal interplay in patients with diabetes." (PMID 40076791, 2025). "Finally, dopamine agonists, in particular cabergoline, improve insulin sensitivity and may exert a positive effect on carbohydrate metabolism in patients with acromegaly, including those with diabetes." (PMID 40142714, 2025). "Studies have found that about 50% of PCOS patients have insulin resistance, of which 30–40% have T2DM, which may be due to a combination of high insulin levels and excessive androgen levels caused by PCOS, resulting in insulin resistance and thus a strong link to the development of diabetes." (PMID 41229546, 2025). "Diabetes Mellitus (DM) is a chronic metabolic condition that develops when the pancreas cannot produce insulin or when the body cannot effectively use the insulin produced." (PMID 41293314, 2025). "This supports the hypothesis that hyperglycemia-induced impairment in insulin signaling exacerbates neuroinflammation and tau pathology and is in line with previous studies showing a link between metabolic dysfunction and cognitive impairment in diabetes." (PMID 40869265, 2025). "Furthermore, the use of continuous glucose monitoring in dogs and cats with diabetes provides real-world data on glucose fluctuation patterns, aiding the refinement of insulin dosing algorithms applicable to pediatric and older adult populations with diabetes in human medicine." (PMID 41012437, 2025). "Similarly, researchers studying diabetes therapies may employ stains to detect insulin- or glucagon-positive cells within explanted devices [21,]." (PMID 40547419, 2025). "Furthermore, γ-ORZ may attenuate cellular apoptosis and improve insulin sensitivity (Rungratanawanich, Abate & Uberti, 2020), both of which are critical factors in the inflammatory cascade of diabetes." (PMID 41018904, 2025). "Diabetes mellitus (DM) continues to pose a growing global health challenge, characterized by chronic hyperglycemia resulting from impaired insulin secretion, insulin resistance, or both." (PMID 41296390, 2025). "However, patients with diabetes mellitus with cirrhosis often require large amounts of insulin." (PMID 40704640, 2025). "Within the diabetic subgroup, insulin therapy was associated with a 52% higher mortality risk compared with patients with diabetes not on insulin, quantifying a clear stepwise gradient from no diabetes through non-insulin-dependent diabetes, and finally to insulin-dependent disease." (PMID 40967652, 2025).
diabetes (continued). "We incorporated related risk factors for OA (diabetes [ebi-a-GCST90013891] and smoking [ieu-b-4857, ukb-b-2047]) along with the use of exogenous insulin (ukb-b-7350) in a multivariable MR analysis to evaluate the direct effect of exogenous insulin use (ukb-b-7350) on OA (ieu-a-1169)." (PMID 41398760, 2025). "Diabetes mellitus (DM) is a chronic metabolic disorder characterized by insufficient production of insulin by the pancreas or by reduced ability to effectively utilize insulin in the peripheral tissues, thus resulting in hyperglycemia." (PMID 40427546, 2025). "Diabetes mellitus (DM) is a complex and multifactorial metabolic disease characterized by high blood glucose levels, resulting from an alteration in the secretion or action of insulin, the hormone responsible for regulating the metabolism of carbohydrates, fats, and proteins." (PMID 41154485, 2025). "The diagnostic criteria, as outlined by the Immunology of Diabetes Society, include a minimal age of 30 years at the onset of diabetes, the presence of at least one circulating islet autoantibody, and a lack of insulin requirement for at least six months after diagnosis." (PMID 41024896, 2025). "For diabetes technology–specific HRSNs, participants (5/17, 29%) acknowledged that digital social needs, such as not having access to a compatible smartphone, impacted whether youth with T1D received the full benefit of the automated insulin delivery system." (PMID 40875986, 2025). "Diabetes mellitus (DM) is a metabolic disease primarily affecting insulin release and blood-glucose homeostasis." (PMID 40969996, 2025). "Diabetes mellitus (DM) is a chronic metabolic disorder characterized by sustained hyperglycemia resulting from impaired insulin secretion, insulin action, or both." (PMID 40722870, 2025). "Type 1 diabetes mellitus (T1DM) is a prevalent form of DM, which displays an absolute dearth of insulin because of damage to the beta cells in the pancreas." (PMID 40244213, 2025). "Diabetes mellitus (DM) is a chronic metabolic disorder characterized by persistent hyperglycaemia resulting from impaired insulin secretion, insulin resistance, or both, leading to disturbances in carbohydrate, lipid, and protein metabolism." (PMID 40569910, 2025). "Diabetes mellitus (DM) is a complex, chronic metabolic disorder characterized by persistent hyperglycemia due to impaired insulin secretion and/or insulin action." (PMID 41011131, 2025). "Diabetes mellitus (DM) is a chronic metabolic disorder characterized by elevated blood sugar levels due to the pancreas's inability to produce sufficient insulin or the body's inability to effectively utilize the insulin produced." (PMID 40786176, 2025). "This includes diabetes knowledge, insulin injection and dose adjustment, and accuracy of blood glucose records, thereby worsening DM and accelerating further cognitive decline." (PMID 41460428, 2025). "Diabetes mellitus (DM) is a chronic metabolic disorder characterized by elevated blood glucose levels due to insufficient insulin production or ineffective insulin utilization." (PMID 40881172, 2025). "Furthermore, CGM could enable more precise titration of insulin or glucose infusion in conditions like diabetic ketoacidosis, hyperosmolar hyperglycemic state, stress- or steroid-induced hyperglycemia, or hyperinsulinism." (PMID 40337990, 2025). "Diabetes mellitus (DM) is a metabolic disorder characterized by elevated blood glucose levels due to either an inadequate response to insulin or insufficient insulin production." (PMID 40535761, 2025). "Prolonged insulin resistance and hepatic induced hyperglycaemia lead to subsequent insulin hypersecretion from the pancreatic beta cells, leading to beta cell dysfunction, not capable of compensating for heightened levels of hyperglycaemia, indicative of diabetes." (PMID 40664615, 2025). "Diabetes mellitus (DM) is a chronic metabolic syndrome characterized by persistent hyperglycemia and insufficient insulin secretion." (PMID 41031371, 2025).
diabetes (continued). "Therefore, in the current study we used a novel tool for the estimation of VAT i.e., METS-VF which utilizes the parameters which remain common clinically available, including fasting glucose, triglyceride, insulin resistance, age, gender, and WHtR with diabetes." (PMID 39932909, 2025). "Early clinical trials confirmed that self-monitoring of glucose could be a feasible and effective approach to promote weight loss and insulin sensitivity in adults without diabetes." (PMID 40338170, 2025). "The combination of CGM with other novel technologies, such as automated insulin delivery systems, and complementing it with behavioral interventions and family support programs is likely to be the secret to maximizing long-term outcomes and quality of diabetes care in general." (PMID 40077058, 2025). "In addition to disease status, seven significant variables were selected: quantitative variables included age, BMI, duration of diabetes, and blood glucose levels, while categorical variables were gender, ethnicity (Kazakh vs. others), and medications taken (insulin vs. other)." (PMID 40231069, 2025). "Furthermore, our results suggest that BACE1 inhibition could be a potential therapeutic target for diabetes mellitus through the restoration of insulin-signaling dysfunction." (PMID 40507910, 2025). "Appetite suppression delayed gastric emptying, and significant reductions in caloric and carbohydrate intake may contribute to increased ketogenesis, particularly in individuals with diabetes or those taking additional medications that affect insulin action or glucose metabolism." (PMID 40507203, 2025). "Therefore, the observed decrease in insulin levels following treatment with “Meein” extract could have broader implications for long-term diabetes management and metabolic health." (PMID 40895680, 2025). "Moreover, targeting RPE insulin pathways may complement systemic diabetes therapies by ensuring that peripheral tissues receive adequate insulin signals independent of pancreatic function." (PMID 41301488, 2025). "Diabetes mellitus (DM) is a globally prevalent metabolic disorder characterized by impaired glucose homeostasis and insulin secretion." (PMID 40408591, 2025). "Finally, five predictors, including duration of diabetes, operation duration, preoperative fasting time, preoperative hypoglycemic regimen (subcutaneous insulin injection), and glucose fluctuation on the day of surgery, were integrated into the predictive model." (PMID 40692592, 2025). "Diabetes mellitus (DM) is a metabolic disorder characterized by chronic hyperglycemia resulting from impaired insulin secretion, impaired insulin action, or a combination of both." (PMID 41011043, 2025). "Manganese activates enzymes such as pyruvate carboxylase, increases insulin secretion, improves glucose tolerance under dietary stress conditions, reduces oxidative stress (ROS) and NADPH oxidase activity, and decreases the risk of endocrine dysfunction in diabetes." (PMID 40224537, 2025). "However, it is unusual to have persistent significant insulin secretion in long-standing diabetes." (PMID 40290321, 2025). "Diabetes mellitus (DM) is a chronic, heterogeneous metabolic disorder characterized by elevated blood glucose levels due to impaired insulin secretion, action, or both." (PMID 41218056, 2025). "Considering insulin’s regulatory effect on FMO3 activity in liver cells, TMAO may serve as a marker of hepatic insulin resistance, which could partially explain its association with diabetes risk." (PMID 40393987, 2025). "Diabetes mellitus (DM) is a chronic metabolic disorder characterized by persistent elevated blood glucose levels and alterations in insulin levels or action." (PMID 40509282, 2025). "Diabetes mellitus (DM) is a chronic metabolic disorder marked by impaired insulin production and/or action, affecting individuals across all age groups—from fetal life to adulthood." (PMID 41185740, 2025).